PCDH10 (protocadherin 10)
Description:
Potential calcium-dependent cell-adhesion protein. (Microbial infection) Acts as a receptor for Western equine encephalitis virus.
Synonyms: KIAA1400; OL-PCDH
Tractability: Antibody: UniProt places it where antibodies can reach, with medium confidence; UniProt predicts a signal peptide or a membrane-spanning region; its Gene Ontology location is reachable by antibodies, with medium confidence. PROTAC: its protein half-life has been measured.
Gene: Protein-coding gene on chromosome 4 (133,149,294 to 133,208,606, forward strand). Ensembl gene ENSG00000138650.
Subcellular location: Cell membrane
Subcellular location (Human Protein Atlas): Golgi apparatus; Nucleoplasm; Vesicles
Gene Ontology:
Molecular function: cell adhesion molecule binding; calcium ion binding
Biological process: cell adhesion; homophilic cell-cell adhesion
Cellular component: plasma membrane; membrane
Genetic constraint (gnomAD): Loss-of-function variants: 12 observed, 65.52 expected, observed/expected ratio (o/e) 0.18, 90% interval 0.12 to 0.3. The upper end of that interval is the gene's LOEUF score, 0.3, which puts it in group 1 of 6, group 1 being the genes least tolerant of losing a copy. Missense variants: 1,203 observed, 1,382.7 expected, observed/expected ratio (o/e) 0.87, 90% interval 0.83 to 0.91. Synonymous variants: 594 observed, 602.54 expected, observed/expected ratio (o/e) 0.99, 90% interval 0.92 to 1.05.
Homologues: Orthologues: chimpanzee PCDH10 (99% identical), macaque PCDH10 (99% identical), guinea pig PCDH10 (98% identical), pig PCDH10 (98% identical), rabbit PCDH10 (98% identical), dog PCDH10 (97% identical), mouse Pcdh10 (97% identical), rat Pcdh10 (97% identical), tropical clawed frog pcdh10 (80% identical), zebrafish pcdh10b (75% identical), zebrafish pcdh10a (75% identical). Paralogues in human: PCDHAC2 (38% identical), PCDHGA12 (37% identical), PCDHGA6 (37% identical), PCDHGA10 (36% identical), PCDHGA1 (36% identical), PCDHGA4 (36% identical), PCDHGA5 (36% identical), PCDHGA8 (36% identical), PCDHGA7 (36% identical), PCDHGC5 (36% identical), PCDHA5 (35% identical), PCDHGA3 (35% identical), and 49 more.
Diseases named in the same sentence as PCDH10 in open-access papers:
PCDH10 is named in the same sentence as 68 diseases in open-access papers, as found by Europe PMC text mining. Sharing a sentence is not in itself a finding about the gene and the disease. The quoted sentences say what the papers report.
gastric cancer (20 papers, 2008 to 2025). A primary or metastatic malignant neoplasm involving the stomach. "For instance, increased PCDH10 promoter methylation was associated significantly with poorer survival of gastric cancer patients, and identified to be an independent prognostic indicator of this cancer type." (PMID 35468745, 2022). "Further evidence that this gene plays an oncosuppressor role derives from the observation that methylation of PCDH10 was associated with poor prognosis in patients with gastric cancer." (PMID 31088413, 2019). "Reduced or suppressed expression associated with methylation of the Pcdh10 promoter has been described in numerous human cancers, including multiple myeloma, gastric cancer (GC), prostate cancer and cervical cancer, where restoration of expression inhibited cell growth and migration." (PMID 39125691, 2024). "The E3 ligase RNF180 ubiquitinates DNMT1, significantly reducing PCDH10 methylation levels and increasing its expression in gastric cancer." (PMID 39048965, 2024). "Further investigations are required to fully understand the function of Pcdh10 in regulating apoptosis in gastric cancer." (PMID 37058252, 2023). "In support of a role for PCDH10 as an oncosuppressor gene, re-expression of this gene by transfection in a gastric cancer cell line inhibited the proliferation, migration, invasion ability, as well as its tumor growth in mice." (PMID 31088413, 2019). "Transcriptional inactivation of tumor suppressor genes, like PCDH10 and RASSF1A, by methylation is associated with progression of gastric cancer, and such methylation can therefore be utilized as a biomarker." (PMID 27330867, 2016). "This was in clear contrast to the 94 and 83% found for gastric cancer cases for PCDH10 and RASSF1A, respectively." (PMID 27330867, 2016). "We demonstrate that the lncRNA MALAT1 recruits EZH2 to repress PCDH10 and promotes gastric cancer metastasis." (PMID 26871474, 2016). "Based on these observations, we proposed a model in which lncRNA MATLAT1 represses PCDH10 and contributes to gastric cancer invasion and migration by recruiting PRC2." (PMID 26871474, 2016). "Conclusions.PCDH10 and RASSF1A methylations in blood samples can serve as potential non-invasive diagnostic indicators in blood for gastric cancer." (PMID 27330867, 2016). "Influence of clinicopathological factor, RASSF1A and PCDH10 methylation on survival of 101 gastric cancer patients." (PMID 27330867, 2016). "It has been reported that in many cancers, including gastric cancer, methylation determined the epigenetic silencing of PCDH10." (PMID 27659532, 2016). "There have been reports about alteration of either PCDH10 or RASSF1A in gastric cancer tissues or cell lines, but none of the studies investigated both genes together." (PMID 27330867, 2016). "For instance, it augments the proliferation of gastric cancer cells by downregulating the expression of miRNAs such as miR-122, miR-1297, miR-22-3p, and miR-202, and by repressing the activity of the oncogene PCDH10, thereby promoting the growth and invasiveness of gastric cancer." (PMID 39336798, 2024). "Pcdh10 expression is silenced or down-regulated in gastric cancer cells and tissues, suggesting it may act as a tumor suppressor in GC." (PMID 37058252, 2023). "Numerous studies have indicated that aberrant methylation of Pcdh10 could be used as a non-invasive biomarker to facilitate diagnosis and prognostic guidance for gastric cancer patients." (PMID 37058252, 2023). "For example, using MSP qPCR method, Pimson and colleagues demonstrated that Pcdh10 promoter methylation was detected in 94.06% of plasma DNA from gastric cancer patients whereas it was found in only 2.97% of matched controls, serving as a reliable non-invasive diagnostic indicator for GC." (PMID 37058252, 2023).
gastric cancer (continued). "Re-expression Pcdh10 in MKN45 gastric cancer cells inhibited tumor growth, cell proliferation and invasion, induced cell apoptosis, and also increased the expression of pro-apoptotic genes including Fas, Caspase8, Jun, and CDKN1A; the anti-proliferation gene FGFR; and the anti-invasion gene HTATIP2." (PMID 37058252, 2023). "LncRNA MALAT1 can promote gastric cancer metastasis by inhibiting PCDH10." (PMID 38003403, 2023). "PCDH10 methylation was higher in precancerous lesions than in chronic gastritis samples and Kaplan–Meier survival curves showed that PCDH10 methylation was associated signif- icantly with shortened survival in stage I–III gastric cancer patients." (PMID 33369468, 2020). "The methylation of PCDH10 is involved in metastasis and has been found in many carcinomas, including colorectal, nasopharyngeal, esophageal, hepatocellular, breast, cervical, and lung cancers, and also in gastric cancer." (PMID 27330867, 2016). "Another study has found that lncRNA MALAT1 promotes the invasion of gastric cancer cells via binding to the core protein complex PRC2 and inhibiting PCDH10." (PMID 29599647, 2018). "Many studies have also observed that the methylation level of PCDH10 and RASSF1A is closely related to gastric cancer tissues, but there are only a few reports of these methylation levels in cell-free DNA." (PMID 27330867, 2016). "Furthermore, the high levels of PCDH10 and RASSFIA methylations in plasma samples from cases suggest an ideal new biomarker for gastric cancer." (PMID 27330867, 2016). "Thus, the aim of this research was to assess the methylation status of PCDH10 and RASSF1A of DNA in blood samples of gastric cancer patients." (PMID 27330867, 2016). "RASSF1A, p14ARF, and MGMT; CHRNA3, DOK1, and GNMT; p16, hMLH1, MINT1, MINT2, MINT12, MINT25, and MINT31; APC, CDH1, MHL1, CDKN2A, CDKN2B, and RUNX3; CDH1; DKK3; PTEN; MGMT; TFPI2; CACNA2D3; PCDH10; SOX2; MAL; and COX2 were previously reported to be hypermethylated in gastric cancer." (PMID 26121593, 2015). "Furthermore, the positive co-expression of RNF180 and PCDH10 is associated with a favorable clinical prognosis in gastric cancer patients, suggesting that PCDH10 and RNF180 could be potential biomarkers for gastric cancer diagnosis." (PMID 39048965, 2024). "Clinical characteristics of 101 gastric cancer patients with and without RASSF1A and PCDH10 methylation in plasma DNA." (PMID 27330867, 2016). "However, with PCDH10, none of the studies about cell-free DNA methylation levels have been measured in blood samples, but in RASSFIA methylation was found in 50 (68.5%) of the serum samples of 73 gastric cancers and, in another study, (34%) of 47 gastric cancers." (PMID 27330867, 2016).
breast carcinoma (11 papers, 2014 to 2026). "Importantly, tumor-associated Pcdh10 methylation status exhibit diagnostic and prognostic value for multiple human cancers, such as colorectal cancer, prostate cancer, cervial cancer, breast cancer, etc.." (PMID 37058252, 2023). "Further evidence that Pcdh10 acts as an oncosuppressor derives from the observations that downregulated Pcdh10 expression caused by methylation predicted poor prognosis in patients with hepatocellular carcinoma, breast cancer, prostate cancer, and non-small-cell lung cancer." (PMID 37058252, 2023). "Our findings reveal a novel PCDH10-dependent tumor-suppressive axis and highlight its potential as a therapeutic target and biomarker in breast cancer." (PMID 41608634, 2026). "Collectively, promoter CpG methylation-mediated silencing of PCDH10 promotes breast cancer progression." (PMID 41608634, 2026). "Frequent PCDH10 downregulation and promoter methylation was identified in breast cancer, correlating with poor prognosis and ER-negative status." (PMID 41608634, 2026). "The main tumor suppressors downregulated in AT are PCDH10 (log2FC − 4.76), a protocadherin whose promoter is methylated in diffuse large B-cell lymphomas or PTPN13 (log FC: − 2.84) an inhibitor of FAS-induced apoptosis associated with aggressive breast cancer." (PMID 34183044, 2021). "Regarding the clinical significance of PCDH10, low PCDH10 levels have been observed in various cancers and have been considered a promising prognostic marker in patients with colorectal cancer, bladder cancer, pancreatic ductal adenocarcinoma, breast cancer, and diffuse large B-cell lymphoma." (PMID 37147733, 2023). "PCDH10 (protocadherin 10) is a potential target for demethylation drugs to achieve its reactivation, which may facilitate the therapies of a wide variety of cancers (e.g. cervical, gastric, colorectal, breast cancers and leukemias)." (PMID 25151146, 2014). "The rate of PCDH10 methylation in CRC tissue was significantly higher compared with normal mucosa in different studies as well as in other types of cancer such as lymphomas, breast cancer and medulloblastoma." (PMID 34277443, 2021).
colorectal cancer (10 papers, 2019 to 2023). A primary or metastatic malignant neoplasm that affects the colon or rectum. "Several studies have reported that aberrant CpG methylation of the Pcdh10 promoter is observed in 43–85% of colorectal cancer tissues, indicating that downregulated Pcdh10 caused by methylation is a common feature of colorectal carcinogenesis." (PMID 37058252, 2023). "The frequent genetic deletion of PCDH10 in colorectal cancers was significantly associated with tumor progression and distant metastasis and found to be an independent predictor of poor survival." (PMID 35468745, 2022). "In line with our findings, a previous study found a significant correlation between PCDH10 methylation and loss of PCDH10 mRNA expression in pancreatic, gastric and colorectal cancers tissues." (PMID 31088413, 2019). "A focal homozygous deletion of PCDH10 was seen in a medulloblastoma patient, and 53 out of 171 colorectal cancer patients showed allelic deletion of PCDH10." (PMID 35468745, 2022). "Interesting recent experiments included knockdown of PCDH10 by shRNA in a T-cell lymphoma cell line, and conditional induction of PCDH10 in a non-small cell lung cancer cell line and a colorectal cancer cell line." (PMID 35468745, 2022). "circ_0001666 can inhibit the progression of colorectal cancer by regulating the miR-576-5p/PCDH10 axis." (PMID 36065412, 2022). "PCDH10 belongs to the protocadherin gene family and acts as tumor suppressor gene inhibiting cell proliferation and cell invasion in colorectal cancer development." (PMID 34277443, 2021). "Notably, PCDH10 promoter methylation had been previously suggested as a prognostic marker in prostate, gastric and colorectal cancer." (PMID 31088413, 2019). "Genetic deletion is pivotal for PCDH10 inactivation in colorectal cancer (CRC), and PCDH10 silencing or downregulation occurs more frequently in tumor cell lines and primary tumors compared to normal mucosa." (PMID 33369468, 2020). "In support of a role for Pcdh10 as a potential antioncogene, re-expressing Pcdh10 in colorectal cancer RKO cells leads to G1 cell cycle arrest without affecting apoptosis." (PMID 37058252, 2023).
autism (9 papers, 2010 to 2023). Persistent deficits in social interaction and communication and interaction as well as a markedly restricted repertoire of activity and interest as well as repetitive patterns of behavior. "Pcdh10 is considered to play important roles in brain development and is implicated in human neurological disorders like autism, obsessive–compulsive disorder, major depression and schizophrenia." (PMID 37058252, 2023). "For example, PCDH10 mutations have been linked to autism, PCDH12 mutations have been associated with schizophrenia and microcephaly and seizures, and PCDH17 mutations have been involved in the pathogenesis of schizophrenia." (PMID 34201522, 2021). "Several studies have identified Pcdh10 act as an autism associated gene." (PMID 37058252, 2023). "It has been reported that the pathophysiology of autism is highly related with homozygous deletion of Pcdh10 in families with ASD." (PMID 37058252, 2023). "For example, prolonged monitoring approaches help to uncover the interplay of genetic factors and time, like in a study of locomotor activity in four genetic mouse models for autism: Shank3−/−, Cntnap2−/−, Frm1−/−, and Pcdh10+/−." (PMID 34630052, 2021). "Protocadherin 10 (PCDH10), which regulates neuronal activity and controls axon outgrowth, is a potential candidate gene for autism." (PMID 24756565, 2014). "Tsai and colleagues identified the autism-related gene Pcdh10 in both a genome-wide screen of MEF2 transcriptional targets and as an FMRP mRNA target." (PMID 23641197, 2013). "Genome association studies have shown that single-nucleotide polymorphisms and deletions in Pcdh genes, such as PCDH10, PCDH11Y and PCDH12, are associated with bipolar disorder, schizophrenia and autism, respectively." (PMID 21824415, 2011). "Studies of large families with shared ancestry have reported several other autism loci including large, inherited, homozygous deletions in neuronal cell-adhesion genes, for example PCDH10 (protocadherin 10)." (PMID 20858243, 2010). "The structural homology, at the basis of grouping protocadherins, particularly that between PCDH10 and PCDH19 that belong to the same δ2 subfamily, further supports a possible and reasonable involvement of the herein-reported PCDH19 in autism." (PMID 36980870, 2023). "Tsai and colleagues elegantly demonstrate roles for several autism-related molecules including myocyte enhancer factor 2 (MEF2), protocadherin 10 (Pcdh10), and fragile X mental retardation protein (FMRP) in a proteasome-mediated pathway that degrades PSD-95 and leads to synapse elimination." (PMID 23641197, 2013).
cervical cancer (7 papers, 2013 to 2024). A primary or metastatic malignant neoplasm involving the cervix. "The methylation status of PCDH10 starts at very early stages of cervical cancer and is highly associated with the severity of the disease." (PMID 35468745, 2022). "In cervical Hela cells, knockdown of HOTAIR lncRNAs inhibits the Wnt/β-catenin signaling cascade by decreasing promoter methylation of Pcdh10, demonstrating the potential mechanism of how Pcdh10 reguates the progression of cervical cancer." (PMID 37058252, 2023). "Since PCDH10 is also silenced in cervical carcinoma, it could be of interest to investigate whether MALAT1 regulation and its effects are somewhat similar in different malignancies." (PMID 28637507, 2017). "Among the 49 PRC2 targets (defined by consistent hyper-MVPs) identified here were 10 genes of the cadherin superfamily in HPV+ HNSCC, including CDH8 and CDH13 (both also hypermethylated in cervical cancer, CDH18, CDH19, CDH23, PCDH10, PCDH15, PCDHB1, PCDHB4, and PCDHB15." (PMID 23419152, 2013).
pancreatic cancer (7 papers, 2019 to 2025). "PCDH10, a member of the protocadherin family, is frequently mutated in pancreatic cancer; it is known as a tumor suppressor and is often silenced by DNA methylation in many types of cancer." (PMID 32520974, 2020). "Pcdh10, or Protocadherin-10, is a tumor suppressor gene that is frequently downregulated by promoter methylation in pancreatic cancer cells." (PMID 41373844, 2025). "The top three genes that were upregulated when the CCK-BR was knocked out of PSCs included Aen, Bok, and Pcdh10; these genes function in pancreatic cancer by increasing apoptosis and tumor suppression." (PMID 41373844, 2025). "Previous study identified that Pcdh10 expression is silenced by methylation in pancreatic cancer cell lines, and re-expression of Pcdh10 prevents the malignant biological process of PC cells." (PMID 37058252, 2023). "In terms of anti-tumor effects, Pcdh10 overexpression can prevent the proliferation, migration, invasion ability of pancreatic cancer cells and trigger apoptosis by activating the AKT pathway." (PMID 37058252, 2023). "Taken together, our findings provide a new FOXM1-miR-552-DACH1/PCDH10/SMAD4 axis to regulate pancreatic cancer cell progression and new opportunities for therapeutic intervention against this disease." (PMID 33867818, 2021). "Of the three criteria, we identified eight genes that were the most highly/frequently methylated in pancreatic cancers (PCDH10, SPSB4, HOXA1, ADAMTS2, BMP3, C13orf18, CCND2, and SEMA5A)." (PMID 32520974, 2020). "Sequencing of the human pancreatic carcinoma cell line Capan-2 showed complete methylation of PCDH10 CpG dinucleotides, as expected for this control cell line." (PMID 31088413, 2019). "This upregulation of miR-552 induced by FOXM1 further inhibited the expression of three downstream targets DACH1, PCDH10, SMAD4, which are known as tumor suppressors in pancreatic cancer progression." (PMID 33867818, 2021). "In summary, this study provides mechanistic evidence for a tumorigenic role of miR-552 in pancreatic cancer and uncovers a novel FOXM1-miR-552-DACH1/PCDH10/SMAD4 axis that promotes pancreatic cancer progression." (PMID 33867818, 2021). "SPSB4 was identified among five genes, ADAMTS2, HOXA1, PCDH10, SEMA5A and SPSB4, that were highly/frequently methylated in liquid biopsies of pancreatic cancers although with a relatively low potential compared with the other four markers." (PMID 34062897, 2021). "In our study, we identified three tumor suppressor genes, DACH1, PCDH10 and SMAD4 as targets of miR-552 in pancreatic cancer." (PMID 33867818, 2021).